ALK (ALK receptor tyrosine kinase)
Diseases named in the same sentence as ALK in open-access papers (continued):
Sharing a sentence is not in itself a finding about the gene and the disease.
neuroblastoma (continued). "Our studies provide the first evidence for neuroblastoma sensitivity to the SHP2 inhibitor TNO155 and its efficacy in combination with ALK inhibitors." (PMID 38032104, 2023). "Xenografts with neuroblastoma cells were treated with the chemotherapeutic drug Temozolomide (under clinical investigation for treatment of refractory/relapsed neuroblastoma: NCT02308527 or NCT01467986) and the ALK inhibitor (ALKi) Ceritinib34,35." (PMID 37202469, 2023). "In the Neuroblastoma case, there are seven conflicting interpretations (KIF1:c.3787 C>T, KIF1B:c.2618C>T, ALK:c.3749T>C, ALK:c.3452C>T, ALK:c.3575G>C, ALK:3383G>C, and ALK:c.3824G>A)." (PMID 37946154, 2023). "Given their positive feedback, there is a possibility that ALK/MYCN cooperativity is involved in the oncogenic metabolic transformation (e.g., elevated glucose uptake/glycolysis and lipid synthesis) of neuroblastoma." (PMID 37414143, 2023). "Such an approach would be of potential benefit to the subset of patients with ALK-driven neuroblastoma who either acquire mutations in the RAS-MAPK pathway as the disease circumvents lorlatinib, or may suggest a strategy for patients who present with dual ALK and RAS-MAPK pathway mutations." (PMID 37147298, 2023). "This is mainly proven by the guided ectopic expression of MYCN (alone or in combination of LMO1 or ALK) in specific cell lineages of zebrafish models or genetically engineered mouse models (GEMM) which results in the development of neuroblastoma." (PMID 37274289, 2023). "In neuroblastomas obtained at diagnosis, we detected SNV in the ALK kinase domain in 10.5% (75/717) of the cases." (PMID 36807339, 2023). "Another study of 23 paired samples revealed ALK mutations in 30.4% at diagnosis and 43.5% at relapse, however, the small patient number limits its informative value on ALK mutation frequencies in relapsed neuroblastoma, and no attempts to assess sub-clonality had been made." (PMID 36807339, 2023). "The endogenous expression of ALK and MYCN in these cell lines was also evaluated in our assay to confirm the different levels of the two genes in the selected neuroblastoma cell lines." (PMID 36585695, 2022). "Taken together, these results suggest that MAPK signaling upon NF1 knockout in neuroblastoma cells harboring ALK mutations is associated with loss of negative ERK-RAF feedback, leading us to hypothesize that these cell lines may be particularly sensitive to MEK inhibitor treatment." (PMID 35689207, 2022). "This presents a potential treatment option for patients with neuroblastomas that have lost NF1 and are resistant to ALK inhibitors, with the potential to impact clinical practice and future clinical trial design." (PMID 35689207, 2022). "Nowadays, different ALK alterations have been detected in several solid tumors such as ACLC, inflammatory myofibroblastic tumors, neuroblastomas, and NSCLC." (PMID 35409355, 2022). "Secondary resistance toward ALK inhibitors is a frequent observation in NSCLC patients and is also seen in neuroblastoma patients, and sometimes the switch to an alternative ALK inhibitor becomes necessary." (PMID 35362827, 2022). "Considering the importance of MYCN and ALK during neuroblastoma tumorigenesis, cell lines with specific genetic alterations of MYCN and ALK have been included." (PMID 36585695, 2022). "Overexpression of MYCN or the constitutively active mutant of ALK, e.g., ALKF1174L, in neural crest cells can induce neuroblastoma in mice." (PMID 36585695, 2022). "Previous studies also reported that ALKAL2 was able to activate ALK in vivo and coexpression of ALKAL2 with ALK was found to promote neurite outgrowth in neuroblastoma cell lines." (PMID 35608912, 2022). "It was also reported that the knockdown of beta-catenin can restore the response to crizotinib in neuroblastoma, which may support the observed positive effect of beta-catenin deficiency in our cohort and imply a strategy of combining inhibitors against beta-catenin and MET/ALK." (PMID 35628499, 2022).
neuroblastoma (continued). "Currently, the clinical outcome of NB is mainly predicted based on age, tumor stage, mitotic nuclear rupture index, MYCN (Neuroblastoma MYC Oncogene) amplification and ALK (Anaplastic Lymphoma Kinase) expression." (PMID 36430219, 2022). "ALK was also identified as major familial neuroblastoma predisposition gene, and as in the previous case, no NB-associated splicing variants have been described." (PMID 36497448, 2022). "If ALK is stimulated, Wnt is also stimulated, leading to the development of NEPC and neuroblastoma in vitro, and tumor growth and metastasis in vivo." (PMID 36358740, 2022). "For neuroblastoma generation, the expression of MYCN oncogene combined with the expression of ALK (anaplastic lymphoma kinase) was induced." (PMID 36142160, 2022). "Only one drug, ALK inhibitor ceritinib (DSP3 hit), substantially decreased the tumor volume in 30% of the INF_R_359_r3 neuroblastoma zPDX models." (PMID 35159116, 2022). "In neuroblastomas, abnormal receptor tyrosine kinase (RTK) activity (e.g., ALK, NTRK) occurs frequently, but the frequency of genetic aberrations of downstream effectors, such as PIK3CA is rather low." (PMID 35159116, 2022). "Activating mutations most often occur in the kinase domain, leading to increased ALK downstream signaling via the PI3K/AKT, RAS/MAPK and JAK/STAT pathways, promoting neuroblastoma cell survival and proliferation." (PMID 35689207, 2022). "They demonstrated that PIM1-mediated ALK inhibitor resistance occurred through the phosphorylation of BAD, resulting in decreased neuroblastoma apoptosis." (PMID 35892829, 2022). "Following the success of ALK inhibitors in non‐small cell lung cancer (NSCLC), clinical trials are ongoing in patients with refractory/relapsed neuroblastoma." (PMID 36029175, 2022). "Moreover, our group showed that neuroblastoma cell lines with elevated (active) tyrosine-phosphorylated ALK present increased levels of (active) tyrosine-phosphorylated GSK3α and GSK3β, raising the possibility that GSK3 may be a direct phosphorylation target of ALK." (PMID 34769149, 2021). "The original reports of ALKAL activation of ALK noted that ALKAL2 was expressed in the adrenal glands and that its expression was observed in neuroblastoma patient samples." (PMID 34885007, 2021). "In neuroblastoma cells, STAT3 has been found to directly bind to full-length ALK, which leads to STAT3 phosphorylation." (PMID 34769149, 2021). "The possibility exists that ALK and PTPN11 are direct substrates of PTPN1 and PTPN2 in neuroblastoma cells." (PMID 34957126, 2021). "Activation or overexpression of ALK has been reported in many types of human cancer, including melanoma, NSCLC, neuroblastoma, glioblastoma, breast, colorectal, and thyroid." (PMID 34884984, 2021). "Here, we focus on anaplastic lymphoma kinase (ALK), which is the most frequent single-gene alteration encountered in primary neuroblastoma." (PMID 34769149, 2021). "In mice, the ectopic expression of neuroblastoma oncogenes, MYCN and (anaplastic lymphoma kinase) ALK, in neural crest precursors was sufficient to drive tumorigenesis in a transplant model." (PMID 34771457, 2021). "What happens in neuroblastoma when the troika of ALKAL2, ALK, and MYCN are aberrantly expressed, or activated, in either 2p-gain or amplification?" (PMID 34885007, 2021). "Here, the authors, through a comprehensive proteomics analysis, identify ATR as a potential therapeutic target of neuroblastoma and demonstrate the efficacy of the ATR inhibitor BAY1895344 in combination with the ALK tyrosine kinase inhibitor lorlatinib." (PMID 34819497, 2021). "In primary neuroblastoma tumours, two neurotrophic factors, pleiotrophin (PTN) and midkine (MDK), are highly expressed and have been postulated to bind and activate ALK in vitro." (PMID 34769149, 2021).
neuroblastoma (continued). "ALK activation has been shown to increase PTPN11 phosphorylation at Y542 and Y580 in a neuroblastoma cell line." (PMID 34569154, 2021). "Here, we investigated ALK and RET in neuroblastoma, with the aim of better understanding their respective contributions." (PMID 33921066, 2021). "ALK has also been shown to drive neuroblastoma formation and to potentiate the oncogenic activity of MYCN in neuroblastoma." (PMID 33585251, 2020). "We previously showed that ALK signals both through the MAPK and PI3K/AKT pathways in neuroblastoma cells." (PMID 31937834, 2020). "A recent study reported that, in ALK mutant, MYCN amplified neuroblastomas, resistance to ALK inhibitors is accompanied by a decrease in MYCN expression and upregulation of the brother of the regulator of imprinted sites (BORIS) protein." (PMID 33291749, 2020). "By exposing neuroblastoma cells to MAPK and PI3K/AKT inhibitors, we confirmed that ALK signals through the MAPK pathway to control ETV5 levels." (PMID 31937834, 2020). "ALK-specific CAR T cells had limited efficacy against neuroblastoma cells, and this was attributed to insufficient ALK target density on neuroblastoma cells to trigger optimal CAR T function." (PMID 32357417, 2020). "After our extensive validation of ETV5 regulation by ALK and RAS/MAPK signalling in neuroblastoma cells, we investigated the contribution of ETV5 to the neuroblastoma cellular phenotype." (PMID 31937834, 2020). "Recently, tunicamycin has been shown to impair also phosphorylation of Anaplastic Lymphoma Kinase (ALK), thus disrupting pro-survival signaling in neuroblastoma cells." (PMID 30979007, 2019). "Chromosomal alterations involving ALK translocations and fusion events have been identified in several cancer types including LUAD, diffuse large B-cell lymphomas, neuroblastoma, and inflammatory myofibroblastic tumors, among others." (PMID 30615629, 2019). "In summary, ALK is abundantly expressed and oncogenic in multiple cancer types affecting children (ALCL and neuroblastomas) and adults (NSCLC and other solid tumors), while it is absent from the majority of normal adult tissues." (PMID 30813562, 2019). "A panel of neuroblastoma cell lines, including CLB-BAR (amplified MYCN/ALK, ALKΔexon4-11), CLB-GE (amplified MYCN/ALK, ALK-F1174V), CLB-PE (amplified MYCN), and IMR-32 (amplified MYCN) was used to test alectinib." (PMID 31334113, 2019). "Ceritinib, which received USA Food and Drug Administration approval in 2014 for treatment of patients with ALK-rearranged metastatic non-small cell lung cancer (NSCLC), has shown efficacy above that of Crizotinib in neuroblastoma models." (PMID 35582571, 2019). "Even when whole-genome sequencing of neuroblastoma was conducted, few recurrent gene alterations (MYCN, ALK, ATRX and TERT) were identified." (PMID 29311760, 2018). "Linking both PHOX2B and ALK biology, some neuroblastoma cell lines, inducing overexpression of PHOX2B, led to increased ALK expression." (PMID 30200332, 2018). "For neuroblastoma cells, MDM2 inhibitors cooperate with anaplastic lymphoma kinase (ALK) inhibition." (PMID 30206211, 2018). "Moreover, people have found that synthesized peptides mimicking the proapoptotic domain of ALK caused cytotoxicity to ALK-positive ALCL and neuroblastoma (NB) cell lines." (PMID 30400214, 2018). "Accordingly, the co-expression of both genes, ALK and HDAC8, was correlated with poor survival of neuroblastoma patients in both cohorts, with long-term overall and event-free survival below 50%." (PMID 29515255, 2018).
neuroblastoma (continued). "Anaplastic lymphoma kinase (ALK) is engaged in the induction and progression of various cancer types, including non-small cell lung cancer (NSCLC), neuroblastomas and lymphomas." (PMID 29455660, 2018). "Consistent with this, neuroblastoma cells with increased ALK activity express high levels of pY-GSK3, and blockade of GSK3 or ALK can affect migration of these cells." (PMID 29555900, 2018). "Studies in neuroblastoma have revealed that R1275Q and wild-type ALK-amplified cell lines are highly sensitive to crizotinib, whereas cell lines harboring the ALK F1174L mutation are less so, but still more responsive to treatment than non-amplified, wild-type ALK cell lines." (PMID 29515255, 2018). "ALK represents a validated therapeutic target in numerous malignancies such as NSCLC, ALCL, IMT and neuroblastoma." (PMID 29495603, 2018). "For instance, studies in multiple models have shown that aberrantly-activated ALK can potentiate the effect of another protein, MYCN, to drive neuroblastoma pathogenesis." (PMID 30400214, 2018). "Finally, we wondered whether PHOX2B protein decrease consequent to CQ and MMF treatment could result in down-regulation of Anaplastic Lymphoma Kinase (ALK) gene expression, whose transcription is PHOX2B-dependent and overexpression is considered pathogenic in neuroblastoma." (PMID 29069774, 2017). "However, upon stimulation with FAM150A (AUG-β) or FAM150B (AUG-α) ligands both ALK-L1198F and ALK-G1201E were able to mediate neurite outgrowth, although at levels less than those observed with wild type ALK or the constitutively active ALK-F1174L neuroblastoma mutant." (PMID 28030793, 2017). "This kind of model has already been successfully developed for ALK-positive ALCL, ALK-positive NSCLC, Rhabdomyosarcoma, and Neuroblastoma, and are considered as the most reliable tumor model." (PMID 29186933, 2017). "Wang and colleagues identified only 3 neuroblastomas harboring ALK amplifications, all also harboring MYCN amplifications, in a cohort of 188 primary neuroblastomas from a patient cohort treated at the Beijing Children’s Hospital." (PMID 29156716, 2017). "Specifically, we found that, for MYCN amplified neuroblastoma, pairwise expression of ACVR2B or anaplastic lymphoma kinase (ALK) with GFRA3, GFRA2, Cadherin 24, or with one another provided the strongest hits." (PMID 28871274, 2017). "We confirmed ALK amplifications in the IMR-32, NB-1 and IMR-5 neuroblastoma cell lines, which were previously reported in the literature." (PMID 29156716, 2017). "Intriguing studies, employing the neuroblastoma SH-SY5Y and IMR-32 cell lines, demonstrated that MDK and ALK are ethanol-responsive and that the activation of ALK signaling by ethanol is dependent on MDK expression." (PMID 28553209, 2017). "Numerous mutations have been observed in the Anaplastic Lymphoma Kinase (ALK) receptor tyrosine kinase (RTK) in both germline and sporadic neuroblastoma." (PMID 29084134, 2017). "Drugs currently under clinical investigation for relapsed/refractory neuroblastoma patients include the mTOR inhibitor, rapamycin (NCT01467986), and the ALK inhibitors, crizotinib (NCT00939770, NCT02559778, NCT01606878, NCT02034981) and LDK378 (NCT01742286)." (PMID 28252645, 2017).
neuroblastoma (continued). "In addition to rare heterozygous PHOX2B mutations detected in neuroblastoma, the pathogenetic role of this gene in neuroblastoma is also indicated by its anomalous overexpression in tumor samples and cell lines, which correlates with the excessive expression of its transcriptional target ALK." (PMID 29069774, 2017). "Crizotinib/PF-02341066 is a small molecule inhibitor targeting ALK and other receptor tyrosine kinases, MET and ROS1, that decreased proliferation in neuroblastoma cell lines with abnormal ALK, particularly those with the R1275Q mutation." (PMID 26771642, 2016). "Neuroblastoma has several autochthonous or companion animal models, the most notable being MYCN- and ALK-expressing mice and zebrafish." (PMID 28035989, 2016). "Of the 16 crizotinib-resistant ALK+ subjects (15 NSCLC and one neuroblastoma) who received 525 mg ASP3026, eight (50 %) achieved PR and seven (44 %) achieved SD at 8 weeks." (PMID 26966027, 2016). "To investigate the effectiveness of PF-06463922 in vivo we orthotopically injected human neuroblastoma cells (CLB-BAR, amplified MYCN/ALK, ALKΔexon 4-11) into the adrenal glands of BalbC/nude mice, prior to treatment with either crizotinib or PF-06463922." (PMID 27483357, 2016). "Taken together, these data demonstrate that the downstream pathways affected by different types of ALK aberration are similar and that ALK promotes cell progression via RAS-JNK-MAP kinase pathways in neuroblastoma." (PMID 27732954, 2016). "In the dose-expansion cohort (crizotinib-resistant ALK-positive; 15 NSCLC; one neuroblastoma), the best overall response was PR in eight patients (50 %) and SD in seven patients (44 %)." (PMID 26966027, 2016). "Among the 16 patients with crizotinib-resistant ALK-positive tumors (15 NSCLC, 1 neuroblastoma), eight patients achieved partial response (overall response rate 50 %; 95 % confidence interval 25–75 %) and seven patients (44 %) achieved stable disease." (PMID 26966027, 2016). "Inhibitors against Anaplastic Lymphoma Kinase (ALK), a transmembrane receptor kinase that belongs to the insulin receptor superfamily, are under clinical evaluation as novel agents to treat neuroblastoma." (PMID 27888620, 2016). "Of the neuroblastoma cell lines tested, both CLB-BAR and CLB-GE are dependent on ALK activity and responded as ALK-addicted cell lines in a manner similar to that previously shown for crizotinib." (PMID 27483357, 2016). "Several reports have shown effective growth inhibition by crizotinib in neuroblastoma, NSCLC, and IBC cell lines harboring ALK copy number gain or amplification in preclinical studies." (PMID 25803816, 2015). "Three main kinases involved in cell survival signaling in neuroblastoma include PI3K/AKT, ALK and FAK." (PMID 26010602, 2015). "Accordingly, we observed an additive effect of TKI/ P36 combination in both ALK-positive ALCL and neuroblastoma." (PMID 25950466, 2015). "ALK, FGFR1, RET, PDGFRA, DDR2, EGFR, and IGF1R were enriched in endosomes from two or more neuroblastoma cell lines, but there were profound differences among cell lines." (PMID 25884760, 2015). "Since MYCN amplification is a well known adverse prognostic marker in neuroblastomas, this provides further support that the ALK D5F3 antibody is likely the most suitable among the three for ascertaining ALK protein expression status as a prognostic biomarker." (PMID 25188507, 2014). "Although selective ALK inhibitors are being evaluated in clinical trials, most of these trials focus on ALK+ solid tumors such as non-small cell lung cancer (NSCLC), neuroblastoma, and inflammatory myofibroblastic tumor." (PMID 25026277, 2014). "Recent work has highlighted the cooperative roles of ALK and MYCN in neuroblastoma, with ALK impacting on both the level of MYCN transcription and the stability of the MYCN protein itself 34–37." (PMID 23889739, 2013).